ANAPC13 (anaphase promoting complex subunit 13)
Description:
Component of the anaphase promoting complex/cyclosome (APC/C), a cell cycle-regulated E3 ubiquitin ligase that controls progression through the cell cycle. APC/C acts by mediating ubiquitination and subsequent degradation of target proteins: it mainly mediates the formation of 'Lys-11'-linked polyubiquitin chains and, to a lower extent, the formation of 'Lys-48'- and 'Lys-63'-linked polyubiquitin chains. APC/C catalyzes assembly of branched 'Lys-11'-/'Lys-48'-linked branched ubiquitin chains on target proteins. APC/C is activated by CDC20 in the metaphase/anaphase transition of cell cycle, targeting the degradation of cyclin B and securin. APC/C is regulated by the mitotic checkpoint complex (MCC), which inhibits APC/C and delays chromosome segregation.
Synonyms: APC13; SWM1; DKFZP566D193
Tractability: No criterion of Open Targets' tractability assessment is met for any kind of drug.
Gene: Protein-coding gene on chromosome 3 (134,477,704 to 134,486,716, reverse strand). Ensembl gene ENSG00000129055.
Subcellular location: Nucleus
Subcellular location (Human Protein Atlas): Cytosol; Mitochondria
Pathways (Reactome):
Immune System: Antigen processing: Ubiquitination & Proteasome degradation
Gene Ontology:
Molecular function: protein binding
Biological process: anaphase-promoting complex-dependent catabolic process; protein branched polyubiquitination; protein K11-linked ubiquitination; protein K48-linked ubiquitination; regulation of meiotic cell cycle; regulation of mitotic cell cycle; protein ubiquitination
Cellular component: anaphase-promoting complex; nucleus
Genetic constraint (gnomAD): Loss-of-function variants: 9 observed, 9.67 expected, observed/expected ratio (o/e) 0.93, 90% interval 0.56 to 1.6. That is too few expected variants to judge how well the gene tolerates losing a copy. Missense variants: 74 observed, 89.27 expected, observed/expected ratio (o/e) 0.83, 90% interval 0.69 to 1.01. Synonymous variants: 30 observed, 31.17 expected, observed/expected ratio (o/e) 0.96, 90% interval 0.72 to 1.3.
Homologues: Orthologues: chimpanzee ANAPC13 (100% identical), dog ANAPC13 (100% identical), guinea pig ANAPC13 (100% identical), macaque ANAPC13 (100% identical), pig ANAPC13 (100% identical), mouse Anapc13 (96% identical), rat Anapc13 (96% identical), tropical clawed frog anapc13 (89% identical), zebrafish anapc13 (82% identical), tropical clawed frog anapc13.2 (74% identical).
Diseases named in the same sentence as ANAPC13 in open-access papers:
ANAPC13 is named in the same sentence as 9 diseases in open-access papers, as found by Europe PMC text mining. Sharing a sentence is not in itself a finding about the gene and the disease. The quoted sentences say what the papers report.
colitis (1 paper, 2024). Inflammation of the colon. "Forced expression of the Anapc13 gene restores the differentiation and ability of Sf3b1K700Efl/+/Foxp3YFP-Cre Tregs to prevent adoptive transfer colitis." (PMID 39303038, 2024). "Furthermore, forced expression of Anapc13 in Sf3b1K700Efl/+/CD4Cre Tregs restores its function in preventing colitis in vivo." (PMID 39303038, 2024).
oral cancer (1 paper, 2020). "Based on genomic to phenomic investigations, we have found new genes including ADCY2, SERPINB5, and ANAPC13 linked with oral cancer that could be potential diagnostic or drug targets." (PMID 32887903, 2020).
cancer (3 papers, 2024 to 2025). A tumor composed of atypical neoplastic, often pleomorphic cells that invade other tissues. "Only 6 CDGs appeared under cell cycle and those were ANAPC13, ANAPC5, MAD2L2, GADD45G, CCND2, and surprisingly MYC — a gene often implicated as a cancer driver." (PMID 39774001, 2025).
tumor (2 papers, 2016 to 2025). "Decreased expression of ANAPC13, at protein and transcript level in tumor, was associated with poor survival in patients with invasive breast tumor and with higher genomic instability in invasive breast tumors, respectively." (PMID 27708222, 2016).
ANAPC13 also shares sentences with these, for which no sentence is quoted: colorectal cancer (1 paper); infertile (1); melanoma (1); prostate carcinoma (1); viral infection (1).